H3C15 (H3 clustered histone 15)
Description:
Core component of nucleosome. Nucleosomes wrap and compact DNA into chromatin, limiting DNA accessibility to the cellular machineries which require DNA as a template. Histones thereby play a central role in transcription regulation, DNA repair, DNA replication and chromosomal stability. DNA accessibility is regulated via a complex set of post-translational modifications of histones, also called histone code, and nucleosome remodeling.
Synonyms: HIST2H3A; H3/n; H3/o
Gene: Protein-coding gene on chromosome 1 (149,852,608 to 149,853,125, forward strand). Ensembl gene ENSG00000203852.
Subcellular location: Nucleus; Chromosome
Subcellular location (Human Protein Atlas): Nucleoplasm
Pathways (Reactome):
Gene expression (Transcription): B-WICH complex positively regulates rRNA expression; DNA methylation; ERCC6 (CSB) and EHMT2 (G9a) positively regulate rRNA expression; MLL4 and MLL3 complexes regulate expression of PPARG target genes in adipogenesis and hepatic steatosis; NoRC negatively regulates rRNA expression; PRC2 methylates histones and DNA; RNA Polymerase I Promoter Escape; RNA Polymerase I Promoter Opening; RUNX1 regulates genes involved in megakaryocyte differentiation and platelet function; RUNX1 regulates transcription of genes involved in differentiation of HSCs; Regulation of endogenous retroelements by KRAB-ZFP proteins; Regulation of endogenous retroelements by Piwi-interacting RNAs (piRNAs); Regulation of endogenous retroelements by the Human Silencing Hub (HUSH) complex; SIRT1 negatively regulates rRNA expression; Transcriptional regulation by small RNAs
Chromatin organization: CHD1 and CHD2 subfamily; CHD6, CHD7, CHD8, CHD9 subfamily; ChAHP complex assembly; Chromatin modifying enzymes; HATs acetylate histones; HDACs deacetylate histones; HDMs demethylate histones; Interaction of NuRD complexes with transcription factors; NuRD complex assembly; PKMTs methylate histone lysines; RMTs methylate histone arginines
Disease: Defective pyroptosis; Dengue Virus-Host Interactions; HCMV Early Events; HCMV Late Events
Signal Transduction: Activated PKN1 stimulates transcription of AR (androgen receptor) regulated genes KLK2 and KLK3; Estrogen-dependent gene expression; Formation of the beta-catenin:TCF transactivating complex; Pre-NOTCH Transcription and Translation
Developmental Biology: Activation of anterior HOX genes in hindbrain development during early embryogenesis; Chromatin modifications during the maternal to zygotic transition (MZT); Transcriptional regulation of granulopoiesis
Immune System: FXIIa activates plasma kallikrein-kinin system; Interleukin-7 signaling; Regulation of PD-L1(CD274) transcription
and 8 more pathways
Gene Ontology:
Molecular function: protein binding; nucleosomal DNA binding; structural constituent of chromatin; DNA binding; protein heterodimerization activity
Biological process: nucleosome assembly; chromatin organization; heterochromatin formation
Cellular component: extracellular exosome; nucleoplasm; nucleosome; nucleus; extracellular region; chromosome
Homologues: Orthologues: Drosophila melanogaster His3:CG33803 (100% identical), macaque H3C13 (100% identical), rat H2bc18 (100% identical), zebrafish hist2h3ca1 (99% identical). Paralogues in human: H3C13 (100% identical), H3C14 (100% identical), H3C1 (99% identical), H3C10 (99% identical), H3C11 (99% identical), H3C12 (99% identical), H3C2 (99% identical), H3C3 (99% identical), H3C4 (99% identical), H3C6 (99% identical), H3C7 (99% identical), H3C8 (99% identical), and 8 more.
Diseases named in the same sentence as H3C15 in open-access papers:
H3C15 is named in the same sentence as 2 diseases in open-access papers, as found by Europe PMC text mining. Sharing a sentence is not in itself a finding about the gene and the disease. The quoted sentences say what the papers report.
alcoholism (1 paper, 2021). "Estrogen signaling pathway was detected and proteins H3C1, H3C13, H3C15 were associated with pathways such as alcoholism, histone modifications, systemic lupus erythematosus." (PMID 33692444, 2021).
H3C15 also shares sentences with these, for which no sentence is quoted: systemic lupus erythematosus (1 paper).